RNU6-760P (RNA, U6 small nuclear 760, pseudogene)
Gene: Small nuclear RNA gene on chromosome 5 (31,832,439 to 31,832,535, forward strand). Ensembl gene ENSG00000251887.
Homologues: Orthologues: chimpanzee U6 (74% identical), macaque U6 (72% identical). Paralogues in human: RNU6-636P (77% identical), RNU6-883P (77% identical), RNU6-138P (76% identical), RNU6-16P (76% identical), RNU6-333P (76% identical), RNU6-38P (76% identical), RNU6-88P (76% identical), RNU6-1127P (75% identical), RNU6-1179P (75% identical), RNU6-1322P (75% identical), RNU6-510P (75% identical), RNU6-1084P (74% identical), and 1284 more.